DOC2B (double C2 domain beta)
Description:
Calcium sensor which positively regulates SNARE-dependent fusion of vesicles with membranes. Binds phospholipids in a calcium-dependent manner and may act at the priming stage of fusion by modifying membrane curvature to stimulate fusion. Involved in calcium-triggered exocytosis in chromaffin cells and calcium-dependent spontaneous release of neurotransmitter in absence of action potentials in neuronal cells. Involved both in glucose-stimulated insulin secretion in pancreatic cells and insulin-dependent GLUT4 transport to the plasma membrane in adipocytes (By similarity).
Synonyms: DOC2BL
Tractability: Antibody: UniProt places it where antibodies can reach, with medium confidence; its Gene Ontology location is reachable by antibodies, with medium confidence.
Gene: Protein-coding gene on chromosome 17 (142,789 to 181,691, reverse strand). Ensembl gene ENSG00000272636.
Subcellular location: Cytoplasm; Cytoplasmic granule; Cell membrane
Gene Ontology:
Molecular function: calcium-dependent phospholipid binding; calcium ion binding
Biological process: calcium ion-regulated exocytosis of neurotransmitter; calcium-dependent activation of synaptic vesicle fusion; intracellular protein localization; positive regulation of calcium ion-dependent exocytosis; positive regulation of insulin secretion; positive regulation of vesicle fusion; chemical synaptic transmission
Cellular component: cytoplasm; plasma membrane; SNARE complex; synapse; membrane; presynapse
Genetic constraint (gnomAD): Loss-of-function variants: 18 observed, 19.46 expected, observed/expected ratio (o/e) 0.92, 90% interval 0.64 to 1.37. The synonymous counts are far from expectation, so gnomAD's model fits this gene poorly and the ratio says little. Missense variants: 349 observed, 286.68 expected, observed/expected ratio (o/e) 1.22, 90% interval 1.12 to 1.33. Synonymous variants: 168 observed, 130.5 expected, observed/expected ratio (o/e) 1.29, 90% interval 1.13 to 1.46.
Homologues: Orthologues: chimpanzee DOC2B (99% identical), macaque DOC2B (98% identical), pig DOC2B (97% identical), dog DOC2B (96% identical), mouse Doc2b (95% identical), rat Doc2b (90% identical), tropical clawed frog doc2b (82% identical), guinea pig DOC2B (73% identical), zebrafish doc2b (71% identical). Paralogues in human: DOC2A (62% identical), RPH3A (61% identical), SYT1 (28% identical), SYT2 (28% identical), SYT6 (27% identical), SYT5 (27% identical), SYT10 (26% identical), SYT7 (26% identical), SYTL4 (26% identical), SYTL5 (25% identical), SYT3 (25% identical), SYT4 (25% identical), and 19 more.
Diseases named in the same sentence as DOC2B in open-access papers:
DOC2B is named in the same sentence as 16 diseases in open-access papers, as found by Europe PMC text mining. Sharing a sentence is not in itself a finding about the gene and the disease. The quoted sentences say what the papers report.
cervical cancer (7 papers, 2014 to 2025). A primary or metastatic malignant neoplasm involving the cervix. "Among various cancers, DOC2B and its functions were primarily studied in cervical cancer; however, causal biological mechanisms and cell signaling pathways leading to functional perturbations were elusive." (PMID 33758996, 2022). "Double C-2 Like Domain Beta (DOC2B) located at 17q13.3 prevents metastasis by senescence induction and epithelial to mesenchymal transition inhibition in cervical cancer (CC)." (PMID 39747389, 2025). "We previously reported the presence of DOC2B in EVs isolated from cervical cancer cell ectopically expressing DOC2B." (PMID 40319292, 2025). "Recent research has identified Double C-2 like domain beta (DOC2B) as a tumor suppressor, exhibiting anti-proliferative, anti-migratory, anti-invasive, and anti-metastatic functions in cervical cancer." (PMID 39179991, 2024). "Our findings suggest that DOC2B acts as a potent tumor growth regulator and confers metastatic resistance via DOC2B-calcium-EMT-senescence axis in cervical cancer." (PMID 33758996, 2022). "Previously, we reported that DOC2B is a methylation-regulated gene, silenced in cervical cancer, and its downregulation is important for the acquisition of key biological characteristics of cervical cancer cells." (PMID 33758996, 2022). "To date, the molecular mechanisms of DOC2B in cervical cancer progression and metastasis is elusive." (PMID 33758996, 2022). "We have previously reported that DOC2B is expressed in normal cervical cells, and its expression is substantially reduced in cervical cancer and cervical cancer cell lines such as SiHa, HeLa, and CaSki by promoter hypermethylation." (PMID 33758996, 2022). "DOC2B is repressed by DNA promoter hypermethylation and functions as a tumor growth regulator in cervical cancer." (PMID 33758996, 2022). "We showed that DOC2B upregulation inhibits metastasis in cervical cancer via two distinct mechanisms: activation of senescence and inhibition of EMT." (PMID 33758996, 2022). "We provide evidence that DOC2B is depressed in cervical cancer due to promoter hypermethylation and act as a novel tumor suppressor gene by regulating multiple pathways in cervical cancer." (PMID 24949095, 2014). "In cervical cancer (CC), Double C2 Like Domain Beta (DOC2B) functions as a metastatic suppressor." (PMID 40319292, 2025). "Primarily, methylation and expression analysis of DOC2B could be used as marker for early diagnosis of cervical cancer." (PMID 33758996, 2022). "Since DOC2B is a suppressor of EMT, analysis of DOC2B expression may be used as a marker to predict metastasis and therapeutic resistance in cervical cancer." (PMID 33758996, 2022). "We propose that targeting DOC2B-calcium-EMT-senescence axis could be potential strategy to develop an effective treatment for metastasis in cervical cancer." (PMID 33758996, 2022). "Collectively, based on the functional role of DOC2B and associated signaling pathways, targeting DOC2B–Calcium–EMT-senescence axis may offer a novel approach for controlling metastasis in cervical cancer." (PMID 33758996, 2022). "Our results demonstrate the novel mechanism of DOC2B-mediated EMT and senescence regulation which can eventually modulate metastasis in cervical cancer." (PMID 33758996, 2022).
diabetes (4 papers, 2021 to 2024). "In line with this, low DOC2b transcript levels have been reported in the islets of diabetic mice, consistent with a link between loss of DOC2b function and pathogenicity of diabetes." (PMID 33673206, 2021). "As expected, other genes (PCK2, DOC2B) pointed at insulin regulation, diabetes and obesity." (PMID 33510859, 2021). "In addition to the regulatory role for STX4 in β-cell inflammatory signaling, DOC2b ameliorates β-cell stress during diabetes." (PMID 33673206, 2021). "Finally, double C2 domain–containing protein β (Doc2b) protects β-cells against inflammatory damage in mice models of diabetes through reducing apoptotic stress." (PMID 33986742, 2021).
Insulin resistance (2 papers, 2022 to 2023). Increased resistance towards insulin, that is, diminished effectiveness of insulin in reducing blood glucose levels. "Discerning strategies to upregulate or stabilize DOC2B protein levels in skeletal muscle could provide avenues to prevent and/or reverse skeletal muscle insulin resistance and halt progression to pre-T2D and T2D." (PMID 38203312, 2023). "Importantly, while overexpression of wild-type DOC2B in L6 skeletal muscle cells prevented insulin resistance, a phosphodeficient mutant of DOC2B, Tyr301Phe, failed in this regard." (PMID 35774142, 2022). "Furthermore, skeletal muscle-specific DOC2B overexpression, induced in adult mice, protects against high-fat diet-induced insulin resistance, even when obesity persists." (PMID 35774142, 2022).
Obesity (2 papers, 2021 to 2023). Accumulation of substantial excess body fat. "Future studies will be needed to evaluate DOC2B protein abundance changes with obesity, pre-T2D, T2D, and Palm-based HFD and discern fiber-type- and muscle depot-related differences." (PMID 38203312, 2023).
cervical tumors (1 paper, 2025). "Targeting mechanisms, such as surface modification or ligand attachment to improve tumor-specific uptake, could enhance the precision of DOC2B-loaded EVs in cervical tumors." (PMID 39747389, 2025).
prediabetes (1 paper, 2022). "Interestingly, DOC2B levels are reduced in T2D human skeletal muscle, suggesting that DOC2B loss could be important for diabetogenesis and implicating DOC2B as a candidate therapeutic target for prediabetes and T2D." (PMID 35774142, 2022).
retinal degeneration (1 paper, 2018). Degeneration of the retina. "Taking into account that deregulation calcium homeostasis plays a key role in retinal degeneration in rd10 mice, pathways involved the regulation, signaling, and/or exocytosis of this cation were also selected for validation, such as those related with Doc2b or Pde6g genes." (PMID 29847644, 2018).
cancer (8 papers, 2014 to 2026). A tumor composed of atypical neoplastic, often pleomorphic cells that invade other tissues. "A protein lacking in abundance in T2D tissues, DOC2B (Double C2 domain-containing protein B), was implicated in mitochondrial function and structure in cancer cells; our preliminary findings indicate that β-cells package DOC2B into the lumen of secreted EVs, by virtue of DOC2B’s tandem C2 domains." (PMID 38338783, 2024). "DOC2B loss in cancer models promotes the formation of filopodia, protrusive structures capable of ECM engagement for matrix metalloproteinase-mediated degradation; similarly, we consider whether changes in β-cells could influence maladaptive interactions with the peri-islet matrix during early T1D." (PMID 42310975, 2026). "Abnormal expression of DOC2B is reported in Cataract 8 Multiple Types, diabetes, and cancer." (PMID 40319292, 2025). "In the present study, we show that DOC2B significantly inhibits cancer cell metastasis in vivo." (PMID 33758996, 2022). "We show for the first time that DOC2B is a metastatic suppressor and propose that reactivation of DOC2B could be used to control cancer metastasis." (PMID 33758996, 2022). "One of the candidate gene identified was Double C2 like Domain beta (DOC2B), a key calcium regulator protein whose alteration has never been linked to cancer." (PMID 24949095, 2014). "While the previous work provided a foundational understanding of DOC2B’s role in oxidative stress and mitochondrial dysfunction, this study extends these findings by elucidating how PC, both in its simple form and within EVs, modulates cancer cell behaviour, particularly in CC models." (PMID 40319292, 2025).
tumor (4 papers, 2022 to 2025). "The present study aims to determine whether ectopic expression of DOC2B causes global metabolomic changes in extracellular vesicles (EVs) and corresponds with its tumor suppressive properties." (PMID 40319292, 2025). "In this study, we investigated how DOC2B localized EVs when transferred to DOC2B-negative SiHa cells, exert tumor suppressive properties using an in vitro model system." (PMID 39747389, 2025). "Here, we examined the tumor suppressive functions of extracellular vesicle DOC2B and explored the potential mechanism in CC." (PMID 39747389, 2025). "Previously, we showed that intracellular calcium is critical for the tumor-suppressive properties of DOC2B in CC18." (PMID 39747389, 2025). "The reintroduction of DOC2B via EVs showed a significant elevation in intracellular calcium levels that correlated with the tumor-suppressive properties of DOC2B." (PMID 39747389, 2025). "More recently, we demonstrated that DOC2B is localized to extracellular vesicles (EVs) and EV mediated DOC2B transfer can inhibit tumor growth in CC." (PMID 40319292, 2025). "The histopathological examination of tumor cryosection showed that DOC2B knockdown increased the number of atypical cells, abnormal nucleus to cytoplasmic ratio, and the density of tumor cells with loosely aggregated cells." (PMID 33758996, 2022). "DOC2B knockdown Cal27 cells formed progressively growing tumors with significantly bigger tumor size and volume when compared with scrambled control cells." (PMID 33758996, 2022). "DOC2B contains calcium sensing and binding domains and may depend on intracellular calcium for several functions, including tumor-suppressive properties." (PMID 39747389, 2025). "Finally, we demonstrated that intracellular calcium chelation significantly reduces DOC2B localization to EVs and impacts its tumor-suppressive properties." (PMID 39747389, 2025). "Our in-vitro findings demonstrate a strong tumor-suppressive effect of DOC2B-loaded EVs." (PMID 39747389, 2025). "Hence, we investigated whether calcium depletion impacts the tumor-suppressive properties of EVs from DOC2B-SiHa cells." (PMID 39747389, 2025). "Therefore, we investigated whether EVs isolated from DOC2B-SiHa cells exhibit tumor suppressive properties compared to EVs from control-SiHa cells by EV transfer experiments." (PMID 39747389, 2025). "Therefore, the tumor-suppressing properties of DOC2B-SiHa EVs in SiHa and HeLa cells may be partly contributed by EV DOC2B." (PMID 39747389, 2025). "Moreover, the presence of DOC2B inhibited in-vivo tumor growth and metastasis." (PMID 40319292, 2025). "Taken together, DOC2B may act as a tumor inhibitory gene in CC." (PMID 40319292, 2025). "The extracellular vesicle (EV) mediated trafficking of DOC2B and its impact on tumor suppressive activity are not investigated in CC." (PMID 39747389, 2025). "Our study shows that DOC2B can be transferred to SiHa and HeLa cells via EVs without compromising its tumor-suppressive functions." (PMID 39747389, 2025). "The H&E staining showed that mice receiving DOC2B-expressing cells displayed no or markedly decreased tumor cells in the liver." (PMID 33758996, 2022).
DOC2B also shares sentences with these, for which no sentence is quoted: breast carcinoma (2 papers); colorectal cancer (1); endometrial cancer (1); lung carcinoma (1); oral cancer (1); osteosarcoma (1); ovarian carcinoma (1).